PET100 (PET100 cytochrome c oxidase chaperone)
Description:
Plays an essential role in mitochondrial complex IV maturation and assembly.
Synonyms: C19orf79; MC4DN12
Tractability: Antibody: UniProt predicts a signal peptide or a membrane-spanning region. PROTAC: ubiquitination databases record sites on it.
Gene: Protein-coding gene on chromosome 19 (7,629,711 to 7,631,956, forward strand). Ensembl gene ENSG00000229833.
Subcellular location: Membrane; Mitochondrion; Mitochondrion inner membrane
Subcellular location (Human Protein Atlas): Mitochondria
Pathways (Reactome):
Metabolism: Complex IV assembly
Gene Ontology:
Biological process: mitochondrial respiratory chain complex IV assembly
Cellular component: mitochondrial inner membrane; mitochondrion; membrane
Genetic constraint (gnomAD): Loss-of-function variants: 14 observed, 13.59 expected, observed/expected ratio (o/e) 1.03, 90% interval 0.68 to 1.6. The upper end of that interval is the gene's LOEUF score, 1.6, which puts it in group 6 of 6, group 1 being the genes least tolerant of losing a copy. Missense variants: 94 observed, 97.01 expected, observed/expected ratio (o/e) 0.97, 90% interval 0.82 to 1.15. Synonymous variants: 28 observed, 32.76 expected, observed/expected ratio (o/e) 0.85, 90% interval 0.63 to 1.17.
Gene-disease validity (ClinGen):
ClinGen rates the evidence that PET100 causes each of these diseases.
mitochondrial disease (autosomal recessive): Definitive.
Leigh syndrome (autosomal recessive): Moderate. A progressive neurological disease defined by specific neuropathological features associating brainstem and basal ganglia lesions.
Homologues: Orthologues: macaque PET100 (92% identical), guinea pig PET100 (84% identical), pig PET100 (84% identical), dog PET100 (82% identical), rabbit PET100 (81% identical), mouse Pet100 (74% identical), rat Pet100 (66% identical), zebrafish pet100 (60% identical), Caenorhabditis elegans Y53F4B.14 (37% identical), Drosophila melanogaster CG14483 (36% identical).
Diseases named in the same sentence as PET100 in open-access papers:
PET100 is named in the same sentence as 4 diseases in open-access papers, as found by Europe PMC text mining. Sharing a sentence is not in itself a finding about the gene and the disease. The quoted sentences say what the papers report.
mitochondrial complex deficiency (1 paper, 2025). "Mutations in genes such as TTC19, SURF1, and PET100, which are associated with mitochondrial complex deficiency, as well as mutations in MT-ND3 linked to mitochondrial DNA-associated Leigh syndrome and NARP, were identified." (PMID 40336053, 2025).
PET100 also shares sentences with these, for which no sentence is quoted: Leigh syndrome (2 papers); cancer (1); neurological disease (1).